TNF (tumor necrosis factor)
Diseases named in the same sentence as TNF in open-access papers (continued):
Sharing a sentence is not in itself a finding about the gene and the disease.
type 2 diabetes (continued). "In addition, a previous study showed that pterocarpan-enriched soy leaf supplementation led to inhibiting the gene expression of TNF-α and IL-6 in the white adipose tissue in type 2 diabetic mice." (PMID 27869712, 2016). "Anti-TNF therapy has been studied in patients with cancer, cardiovascular disease, as well as kidney disease, whether also anti-TNF therapy can be beneficial in Type 2 diabetes remains, as far as we know, to be studied." (PMID 26928194, 2016). "Interestingly, high levels of TNF-α were shown to inversely correlate with immune activation in healthy donors and in patients with type 2 diabetes." (PMID 27285580, 2016). "It is noteworthy that the concentration of CRP, IL-6 and TNF observed in this study appeared to be slightly larger than the values found in Chinese patients with type 2 diabetes or coronary heart disease and in the prospective Multi-Ethnic Study of Atherosclerosis." (PMID 26080804, 2015). "The adipokine tumor necrosis factor-α (TNFα) is involved in the development of type 2 diabetes." (PMID 26106437, 2015). "Both alpha-tocopherol and ascorbic acid could significantly diminish serum levels of TNF-α in patients with type 2 diabetes." (PMID 26693410, 2015). "In the LPS study, patients with type 2 diabetes and healthy controls were administered an LPS bolus of 0.3 ng/kg, which induced an inflammatory response with increased body temperature, heart rate, neutrophil count, and TNF-α and IL-6 levels." (PMID 25104880, 2014). "Confirming these results, other studies have shown that subclinical systemic inflammation in obese patients, as measured by elevated levels of CRP, IL-6, and TNF-α, predicts the development of type 2 diabetes and contributes to a decrease of insulin sensitivity in peripheral tissues." (PMID 25548896, 2014). "The HFCS-treated rats have higher TNF-α, observed in obese and type 2 diabetes patients." (PMID 24481132, 2014). "We, therefore, sought to investigate the effects of a three-weekly aerobic-training programme, without a concomitant weight loss diet, on circulating levels of plasma biomarkers of MDA and TNF-α in type 2 diabetic patients, who were free of known cardiovascular disease." (PMID 27437465, 2014). "It was demonstrated that CTB-APSL fusion protein could effectively improve the inflammatory response in type 2 diabetic mice by reducing the levels of the inflammatory cytokines TNF-α and IL-6." (PMID 24633252, 2014). "The aim of the present study was to explore whether different features of type 2 diabetes (hyperinsulinemia, hyperglycemia and tumor necrosis factor alpha [TNF-α]) protect against the development of prostate cancer." (PMID 24058525, 2013). "Thus, it appears that retrograde inflammation has strong contribution to SVI in FDR of type 2 diabetics, in which TNFα plays a pivotal role." (PMID 24265679, 2013). "Interestingly the observed responses in PGC-1α MKO and to some extent whole body PGC-1α KO mice, resemble the previously reported attenuations in LPS-induced plasma TNFα response in type 2 diabetes patients." (PMID 22384185, 2012). "In addition, TNF-α production by monocytes was assessed by quantitative real time PCR (qPCR), and monocytes from patients with type 2 diabetes had significantly elevated levels of TNF-α mRNA than controls (P < 0.05)." (PMID 22500980, 2012). "All of the pro-inflammatory cytokines evaluated (IL-1β, IL-6, IL-8, IL-10, IL-12p70, and TNF-α) were increased in patients with type 2 diabetes, although only the increases in TNF-α, IL-8, and IL-12 p70 were statistically significant in comparison to healthy individuals (P < 0.05)." (PMID 22500980, 2012). "We previously found that TNF system activities are independently associated with pulse wave velocity in non-obese Japanese type 2 diabetic patients." (PMID 22117840, 2011). "Pro-inflammatory cytokines such as TNF-α may play a significant role in the development of renal injury in type 2 diabetes." (PMID 23554718, 2011).
type 2 diabetes (continued). "We now report a sub-study of the parent study, where our current goal is to simultaneously measure the changes in plasma hsCRP, TNF-α and interleukin-6 after a mixed-meal breakfast in patients with Type 2 diabetes and relate these changes to those of post-meal glucose, insulin and triglycerides." (PMID 21517955, 2011). "This is the first study to show that controlling post-meal hyperglycaemia with a prandial + basal insulin regimen vs. a basal insulin regimen can attenuate the meal-induced increases in hsCRP, interleukin-6 and TNF-α in patients with Type 2 diabetes on metformin." (PMID 21517955, 2011). "Therefore, the present investigation was designed to study the action of aqueous extract of P. marsupium on TNF-α activity in type 2 diabetic rats." (PMID 21189913, 2010). "One can speculate that, childhood filarial infection reduces TNF-α, IL-6 and GM-CSF levels thereby conferring protection against type-2 diabetes." (PMID 20559443, 2010). "Interestingly, in patients with type 2 diabetes, serum HER-2 concentrations were positively associated with serum soluble tumor necrosis factor-α (TNF-α) receptor 1 [r = 0.65, p = 0.001, n = 21] and serum DLK-1 (r = 0.81, p = 0.007, n = 9) (data not shown)." (PMID 20184722, 2010). "Moreover, KBG has a favorable effect on impaired glucose metabolism in type 2 diabetes by improving glucose intolerance, and it has been suggested that some of this effect is derived from the reduction of TNF-α content in skeletal muscle." (PMID 21253500, 2010). "While current guidelines for treating PDN only use neuropathic pain regimens, our results suggest that a combination of both neuropathic and anti-inflammatory therapies that target COX2, iNOS, and TNF-α will improve the current standard treatment for PDN of type 2 diabetes." (PMID 20482876, 2010). "P. marsupium modulates the inflammatory cytokine TNF-α in type 2 diabetic rats." (PMID 21189913, 2010). "Since serum levels of MCP-1 are elevated in patients with type 2 diabetes, as are levels of TNF-α and interleukin-6, it is conceivable that diabetics mount an exaggerated immune response to C. neoformans (paradoxical to their defective immune state) leading to fatal outcomes." (PMID 19946453, 2009). "Based on these observations, we sought to investigate the impact of unsaturated fatty acids such as oleic acid in the presence of TNF-α in terms of insulin production, the molecular mechanisms involved and the in vivo effect of a diet high in oleic acid on a mouse model of type II diabetes, KKAy." (PMID 19558671, 2009). "Interestingly, similar localization within/around islets was also described in NOD mouse and type 2 diabetic humans, and it is known that pro-inflammatory cytokine activities, like those of IL-1β and TNF-α, involve ROS generation." (PMID 19654863, 2009). "We have demonstrated that resistin mRNAexpression from human peripheral monocyte-enriched mononuclear cells iselevated in type 2 diabetic women, compared to healthy control women, inparallel with significant increases in mononuclear IL-1β, TNF-α, and IL-6 mRNAexpression." (PMID 19125180, 2008). "These abnormalities may be atherogenic, and overexpression and release of TNF-α may have a role in the development of insulin resistance and Type 2 diabetes." (PMID 17714581, 2007). "The elevated plasma levels of soluble TNF-α and some adhesion molecules in Type 2 diabetes could imply increased activity or expression of ADAMs in these observations." (PMID 17714581, 2007). "Despite these difficulties, the fact that adipokines were measurable in saliva in some studies (e.g., resistin, visfatin, TNF-α and ghrelin levels in unstimulated whole saliva in type 2 diabetes) may be related to the investigators’ use of specialized assay kits designed for saliva samples." (PMID 40142334, 2025).
type 2 diabetes (continued). "Moreover, the elevated plasma levels of C-reactive protein (CRP) and other pro-inflammatory cytokines such as interleukin-6 (L-6) and Tumor necrosis Factor-alpha (TNFα) were reported to induce pancreatic beta cell atrophy and dysfunction in type 2 diabetic rats." (PMID 39859066, 2025). "Moreover, the increased level of this interleukin may have a beneficial effect on health because its heightened level in individuals with type 2 diabetes inhibits the production of pro‐inflammatory factors: TNF‐alpha and indirectly IL‐1." (PMID 38639648, 2024). "Previous research found a significantly lower serum TNFα level in the vitamin D supplementary group comparing with the control group within a cohort of type 2 diabetes patients, suggesting that the vitamin D supplementation may have contributed to this difference." (PMID 38017461, 2023). "Studies have indicated that myosteatosis is associated with insulin resistance, type 2 diabetes mellitus (T2DM), dyslipidemia and cardiometabolic diseases, and there was also a link between skeletal muscle density and biomarkers of inflammation, such as CRP, IL-6, TNF-α, adiponectin and leptin." (PMID 35837298, 2022). "Moreover, a dysregulated immune system in patients with type 2 diabetes and chronic inflammation accompanied with elevated cytokine levels such as interleukin-6, tumor necrosis factor-α, and C-reactive protein could promote CRC tumorigenesis." (PMID 39131121, 2022). "Studies have shown that obese people with type 2 Diabetes Mellitus (T2DM) may have impaired innate/adaptive immunity, which is a result of the production of several pro-inflammatory cytokines (INF-γ, TNF-α, IL-1) due to which they may be more susceptible to a severe COVID-19 infection." (PMID 35603097, 2022). "Patients with type 2 diabetes mellitus (T2DM) also showed significantly elevated serum CML and hs-CRP with a remarkable increase in TLR-4 expression and IL-6 and TNF-α, suggesting that high level of CML is associated with pro-inflammatory cytokines." (PMID 36077532, 2022). "In addition to the TNFR1 signaling, TNF has been reported to mediate Aβ-induced activation of dsRNA-dependent protein kinase (PKR), which underlies the shared pathogenic mechanisms between AD and type-II diabetes." (PMID 34625123, 2021). "Consistently, the ccf-DNA (ccf-DNA #1 and ccf-DNA #2) from two independent patients with type 2 diabetes showed significantly higher IL-1β and IL-18 secretion in response to poly(dA:dT) as compared with the vehicle control, whereas the secretion of tumor necrosis factor (TNF)-α was unchanged." (PMID 30965677, 2019). "Treatment with pentoxifylline, a drug that can inhibit TNFα production, significantly reduced albuminuria and slowed estimated glomerular filtration ratio (eGFR) decline in patients with type 2 diabetes (T2D) and stage 3–4 CKD2." (PMID 30333553, 2018). "Among subjects at higher risk of type 2 diabetes, an acute postprandial intervention of MUFA breakfast (72 E%) containing macadamia nut oil showed that several inflammatory genes were upregulated in subcutaneous adipose tissue (MCP-1, IL-1β, IL-6, IL-6R, TNF-α and TNFRSF1A)." (PMID 28076613, 2017). "Furthermore, it has been reported that the increase in pro-inflammatory cytokines such as interleukine-1 (IL-1), tumor necrosis factor alpha (TNF-α) and interleukin 6 (IL-6) in a type 2 diabetic state is commonly accompanied by a decrease in cellular antioxidant levels and increased apoptosis." (PMID 28933769, 2017). "Moreover, aspirin has been shown to reduce TNF-α in patients with type 2 diabetes." (PMID 26928194, 2016). "Elevated levels of circulating inflammatory cytokines, including nuclear factor kappa-light-chain-enhancer of activated B cells (NF-κB) and tumor necrosis factor-alpha (TNF-α), in patients with postprandial hyperglycemia, may serve as predictors of the risk of type 2 diabetes." (PMID 26877773, 2016).
type 2 diabetes (continued). "This inflammation is associated with macrophage infiltration into adipose tissue and macrophage-derived secretion of pro-inflammatory cytokines (e.g. TNF-α, IL-6), which promote insulin resistance and might have direct implications in obesity related disease, particularly Type 2 Diabetes (T2DM)." (PMID 24983948, 2014). "Interestingly, serum TNF-α levels are also higher in type 2 diabetes patients." (PMID 25548896, 2014). "In addition, our data were strengthened by the use of three different reference genes, as well as a positive control gene, namely TNF-alpha, which has been repeatedly reported to be up-regulated in patients with type 2 diabetes and in vitro high glucose conditions." (PMID 23894607, 2013). "Activation of TNF-TNFR axis in response to elevated Tumor Necrosis Factor α (TNFα) levels, a pro-inflammatory cytokine, can be speculated to contribute to the causation of type 2 diabetes." (PMID 21849023, 2011). "Moreover, proinflammatory cytokines, such as TNF-α, could promote the expression of fgl2 in renal capillaries of rats with type 2 diabetes." (PMID 23554679, 2011). "In addition, it was also noted that TGFBR1 (transforming growth factor-β receptor 1), which is an anti-inflammatory cytokine that inhibits the production of pro-inflammatory cytokines such as IL-6 and TNF-α was found to be up regulated in type 2 diabetes, most probably as a compensatory mechanism." (PMID 18078524, 2007). "Biomarkers such as TNF-α, CRP, and IL-6 showed strong correlations with nausea, diarrhea, abdominal pain, and bloating, with the most severe symptoms observed in the ART + type II diabetes group." (PMID 39860995, 2025). "Our results corroborate these findings, as both the ART and ART + type II diabetes groups exhibited consistently elevated levels of inflammatory biomarkers, including CRP, IL-6, TNF-α, and fibrinogen, compared to the control group." (PMID 39860995, 2025). "In patients with type 2 diabetes, SGLT2 inhibitors decrease the levels of proinflammatory cytokines (TNF-α, IL-6, and IL-1β) and attenuate the activity of NLRP3 inflammasome." (PMID 40004134, 2025). "Firstly, it provides new insights into the correlation between elevated inflammatory biomarkers—such as CRP, IL-6, TNF-α, and fibrinogen—and gastrointestinal symptoms in HIV-positive patients on ART, particularly those with type II diabetes." (PMID 39860995, 2025). "Chronic low-grade inflammation in type 2 diabetes activates MAPK signaling and increases cytokines such as TNF-α, IL-6, and IL-8, which enhance thyroid cell proliferation, angiogenesis, and survival, favoring tumor development." (PMID 41515940, 2025). "Wang’s animal study stands alone in demonstrating the increased expression of pro-inflammatory cytokines TNF-α, IL-6 and IL-1β and the decreased expression of anti-inflammatory cytokines IL-4 and IL-10 in the midbrain of MPTP-treated type 2 diabetic mice." (PMID 40672460, 2025). "The connection between well-known inflammatory markers such as C-reactive protein (CRP), IL-6, IL-8, TNF-α, and endothelin-1 and DAN has been established in patients with type 1 and type 2 diabetes." (PMID 40137134, 2025). "In PLWH with MASLD or type 2 diabetes, lipotoxicity, oxidative stress, and activation of the NLRP3 inflammasome amplify the production of inflammatory cytokines (IL-6, TNF-α), with deleterious effects on mitochondrial function and immune homeostasis." (PMID 41153793, 2025). "Elevated levels of pro-inflammatory factors, including TNF-α, IL-6, and ICAM-1, can have a predictive role for the development of diabetic neuropathy in type 2 diabetic patients." (PMID 39596058, 2024).
type 2 diabetes (continued). "Systemic levels of TNF-a, IL-1b, IL-6, and CRP are elevated in both type 1 and type 2 diabetes patients, which is a result of the chronic activation of pro-inflammatory pathways within insulin-target cells." (PMID 38904046, 2024). "In four out of five cytokines (IL-6, IL-8, TNF-α, and IFN-γ), serum concentrations were higher in type 2 diabetes compared to type 1 (p < 0.003)." (PMID 37189645, 2023). "White adipose tissues are a major source of inflammatory cytokines (e.g., TNFα, IL1, IL6, and others) and play a critical role in the development of type 2 diabetes." (PMID 37895942, 2023). "This evidence suggests a probable pathway that links TNF-α and TCF7L2 in the co-existence of malaria and type 2 diabetes." (PMID 37215099, 2023). "Clinical data also show that systemic levels of pro-inflammatory cytokines, including tumor necrosis factor (TNF)-a, interleukin (IL)-1b, IL-6, and CRP are elevated in patients with both type 1 and type 2 diabetes." (PMID 36769405, 2023). "For instance, patients with type II diabetes mellitus exhibited the overexpression of various pro-inflammatory M1 polarisation markers [CD16, interleukin-6 (IL-6), iNOS, tumor necrosis factor-α (TNF-α), and CD36] in their PBMCs compared to healthy subjects." (PMID 37375598, 2023). "The expression and clinical significance of tumor necrosis factor-α (INF-α) and interleukin 1-β (IL-1β) in retinal cells of patients with type 2 diabetes (T2DM) retinopathy were detected by flow cytometry." (PMID 35979044, 2022). "Specifically, previous publications have described that weight loss due to calorie restriction reduces oxidative stress and adipose tissue inflammasome activation in mice and humans with type-2 diabetes, which is reflected in reductions of CRP and TNFα levels." (PMID 35158762, 2022). "Metformin significantly reduced proinflammatory markers (IL-6, TNF-α, CRP) in the serum of type 2 diabetic patients and suppressed NF-κB levels in the context of diabetes and intestinal inflammation through AMPK-independent and -dependent processes." (PMID 35855344, 2022). "Type 2 diabetes-induced liver damage is almost always accompanied by severe hepatic inflammation characterized by the expression increases of ICAM-1, TNF-α, and PAI-1." (PMID 34307690, 2021). "We observed a high correlation between BW of type 2 diabetic rats and FBG, TG, LDL-C, leptin, insulin, and TNF-α." (PMID 34039404, 2021). "In both the type 2 diabetes and metabolic syndrome models, treatment with the CCL4 antibody increased pancreatic insulin expression, and reduced circulating insulin, TNF-α, and IL-6 levels." (PMID 33968046, 2021). "In the mechanism analysis, we focused on inflammation, especially tumor necrosis factor-α (TNF-α), based on the report that inflammation is induced in type 2 diabetes patients and that TNF-α regulates the expression of skin AQP3." (PMID 33494453, 2021). "The activation of SOD and inhibition of MDA, IL-6, TNF-α, MCP-1 and cyclooxygenase-2 (COX-2) also indicated the mitigation of oxidative stress and inflammation, which is closely related to type 2 diabetes." (PMID 33435282, 2021). "Our findings indicate that AMGB has the potential to control TNF-alpha, mTOR, extracellular signal-regulated kinases (ERK), IRS, and PI3K, consequently improving the insulin signaling pathway and preventing type II diabetes mellitus." (PMID 34944525, 2021). "Treatment with SIT considerably decreased the gene expression of TNF-α and IL-6 in the adipose tissue of HFD and sucrose induced type-2 diabetic rats." (PMID 33917607, 2021). "An important observation in our study is that SIT acts as effectively as metformin to normalize the serum adipokine levels including leptin, resistin, adiponectin, TNF-α, IL-6, SREBP-1c and PPARγ in HFD and sucrose induced type 2 diabetic rats." (PMID 33917607, 2021).